IL6 (interleukin 6)
Diseases named in the same sentence as IL6 in open-access papers (continued):
Sharing a sentence is not in itself a finding about the gene and the disease.
COVID-19 (continued). "In early COVID-19, the initial host response in the lung involves the release of large amounts of cytokines, including interleukin-6." (PMID 41141600, 2025). "In our study, endothelial dysfunction, as evidenced by reduced FMD, was inversely correlated with serum IL-6 levels in patients with moderate COVID-19." (PMID 40143236, 2025). "For the IL6 gene, intronic variants have been related to respiratory diseases, including ARDS and COPD, with the GG genotype of rs1800795 associated with severe COVID-19 cases among Kurdish patients." (PMID 40506975, 2025). "IL6 emerged as a central hub gene consistently expressed in both lung and brain tissues of deceased COVID-19 patients, underscoring its role in driving the inflammatory pathophysiology of COVID-19 within these organs." (PMID 41141600, 2025). "More specifically, early intervention with IL-1 and IL-6 inhibitors has shown promise in improving outcomes for COVID-19 patients with hyperinflammatory disease and severe pneumonia." (PMID 40497938, 2025). "Recent investigations in sepsis, ARDS, and COVID-19 have consistently shown that integrating IL-6 with cytokines, such as IL-8, TNF-α, and IL-10, enhances discrimination for mortality, organ failure, and disease severity." (PMID 41155261, 2025). "Peripheral insulin resistance leads to the risk of cardiovascular events through the increase of inflammatory markers, IL-6 and Il-1, treated with glimepiride, in 50 patients with cancer infected with COVID-19." (PMID 40599143, 2025). "This study aims to addresses two important gaps in knowledge by comparing novel inflammatory markers (HBP and SAA) against established markers (IL-6 and CRP) to characterize inflammatory phenotypes associated with tissue damage and viral load in COVID-19." (PMID 40621180, 2025). "Case reports of ECMO-integrated CytoSorb® have documented brisk interleukin-6 clearance and catecholamine sparing, and the multi-centre CytoSorb Therapy in COVID-19 Registry reported 74% 90-day survival when adsorption was initiated within 24 h of cannulation." (PMID 40565970, 2025). "Previous reports have shown that the pathogenesis of COVID-19 is supported by a potent inflammatory response involving various mediators, such as IL-6 and IL-10." (PMID 41583455, 2025). "IL-6 levels are significantly increased in lung cancer patients with COVID-19, and these factors induce a cytokine storm that leads to acute respiratory distress syndrome." (PMID 40236655, 2025). "COVID-19 patients have elevated serum levels of complement proteins like C5a, which can boost IL-6 and TNFa expression." (PMID 40552181, 2025). "A weaker, yet still observable, association was found for other factors such as C-peptide, ApoB, COVID-19 severity, T2D duration, IL-6, cholesterol, and BMI." (PMID 40950970, 2025). "Elevated levels of inflammatory markers and interleukin-6 (IL-6) were observed in both waves of COVID-19." (PMID 40284924, 2025). "During acute COVID-19, CD25 levels were positively associated with several serum inflammation markers, including C-reactive protein (CRP), IL-1β, IL-6, IL-10, and tumor necrosis factor (TNF)." (PMID 41310351, 2025). "Production of inflammatory mediators IL-12p70, IL-6, IL-1β, IL-2, and IL-1ra in individuals with flu-like symptoms and those with COVID-19 was higher among residents in endemic areas than in residents from a control non-endemic area." (PMID 40165959, 2025). "In order to complete the inflammatory response evaluation, sCD14ST was also correlated with the primary cytokine IL-6, one of the main mediators of the COVID-19-induced “cytokine storm”." (PMID 39941649, 2025). "IL-6 contributes to the inflammation and severity resulting from COVID-19, and its blockade controls the cytokine storm." (PMID 40172196, 2025). "Immunomodulatory therapies, including dexamethasone and inhibitors targeting interleukin-6 or Janus kinase, are particularly effective in treating severe or critical cases of COVID-19." (PMID 39806466, 2025).
COVID-19 (continued). "We suggest that measuring circulating levels of IL-6 and IL-10 should be implemented and routinely quantified for patients with pneumonia and suspected COVID-19." (PMID 40508859, 2025). "IFNγ, CXCL10, and IL-6 are among many elevated proteins at baseline in all COVID-19 positive subjects relative to healthy subjects." (PMID 40424310, 2025). "COVID-19 can activate the NF-κ B pathway by generating ROS, leading to the release of inflammatory cytokines (IL-1, IL-6, and TNF-α)." (PMID 41156098, 2025). "Associations between severe COVID-19 and elevated levels of pro-inflammatory cytokines like IFN-γ, TNF-α, and IL-17 and anti-inflammatory cytokines including IL-6 and IL-10, have been reported." (PMID 40934185, 2025). "IL-6, primarily secreted by monocytes and macrophages, is recognized as a vital driver of the cytokine storm in COVID-19 patients, exacerbating disease progression and leading to more severe symptoms and higher mortality." (PMID 40370439, 2025). "This is corroborated by data on the correlation between miR-146a-5p and IL-6 levels in COVID-19 patients." (PMID 41155393, 2025). "This process was found to be dependent on the cytokine Interleukin-6 (IL-6), which plays a central role in COVID-19 pathogenesis." (PMID 41472277, 2025). "The oral administration of enteral formulas has been reported to reduce the pro-inflammatory cytokine IL-6 and C-reactive protein levels in patients with severe COVID-19." (PMID 40002722, 2025). "Compared to the cured and discharged COVID-19 patients (n = 54), expression levels of miR-155 and IL-6/IL-10 ratio were significantly higher in patients who died (n = 21) (p-values = 0.001), while serum level of IL-10 was significantly lower (p-value < 0.001)." (PMID 41203712, 2025). "IL-6 acts as a major player in the systemic effect of the pro-inflammatory acute inflammatory response, and it has recently been described as a COVID-19 severity predictor." (PMID 39941649, 2025). "Systemic inflammation in COVID-19 triggers the release of pro-inflammatory cytokines (IL-6, TNF-α, IL-1β), impairing cardiac function directly and by promoting inflammatory cell infiltration." (PMID 40142859, 2025). "IL-33 activation has been reported in advanced COVID-19, contributing to severe lung inflammation by activating several proinflammatory cytokines such as IL-6 and TNF-α through the MyD88-MAPK-NF-kB signaling axis." (PMID 40242753, 2025). "IL-6 remains the best available biomarker to monitor the severity of COVID-19; it has great potential for guiding disease treatment." (PMID 39925527, 2025). "High IL-6 levels correlate with disease severity, including risks of mechanical ventilation and mortality in COVID-19." (PMID 41012595, 2025). "This study was conducted to investigate the associations between polymorphisms in the TNF-α, IL-6, IL-8, IL-10, and CCL5 genes and COVID-19 severity." (PMID 40881695, 2025). "Some differentially expressed genera in COVID-19 patients correlated with inflammatory IL-6 concentrations, including Gemella (r = 0.58; p = 0.025), Lactonifactor (r = −0.58; p = 0.025), and Anaerobutyricum (r = −0.52; p = 0.042)." (PMID 40572294, 2025). "One of the key drivers of organ damage in severe COVID-19 is the cytokine storm—an exaggerated systemic inflammatory response characterized by the release of high levels of proinflammatory cytokines such as IL-6, TNF-α, and IL-1β." (PMID 40430148, 2025). "In relation to PCC, IL-6 has been suggested as a potential mediator of long-term neuropsychiatric symptoms of COVID-19." (PMID 41323348, 2025). "Due to their central roles in driving harmful inflammation and downstream pathological cascades, TNF-α, IL-6, and IL-1 have been extensively investigated as therapeutic targets in sepsis and other cytokine storm-related conditions, such as severe COVID-19." (PMID 41157235, 2025).
COVID-19 (continued). "Compared to age- and sex-matched controls, LC patients with mild–moderate COVID-19 had inflammatory mediator levels 8 months post-infection, including IL-6 and INF-γ, that were consistent with immunological dysfunction.." (PMID 40563736, 2025). "At the height of the COVID-19 pandemic, risk stratification was based on simple clinical parameters (age, comorbidities, etc) as well as markers of inflammation such as CRP and IL6." (PMID 40173171, 2025). "According to our results, it is reasonable to assume that the induction of EndMT in COVID-19 is also ascribable to the presence of several cytokines secreted by macrophages in CM_S1 medium, including IL-1β, IL-6, TNFα, and IFNγ." (PMID 40943589, 2025). "Small COVID-19 series and case reports have described rapid falls in IL-6, CRP, and D-dimer after TPE, occasionally accompanied by transient haemodynamic and oxygenation improvement, but these observations are heterogeneous and often uncontrolled." (PMID 41517263, 2025). "Anti-IL-6-receptor therapy such as tocilizumab in patients with COVID-19 with high levels of IL-6 has shown to be beneficial by potentially blocking the inflammatory cascade." (PMID 38396460, 2024). "Prior studies on the innate immune response in COVID-19 patients have noted an increase in total neutrophils, serum interleukin-6 (IL-6), and C-reactive protein (CRP), along with a decrease in total lymphocytes." (PMID 38655258, 2024). "Circulating levels of IL-6 have been described as an important indicator of mortality in severe COVID-19." (PMID 38732160, 2024). "Secondly, it was not our intention to make a direct comparison between the two entities, but rather to analyze IL-6 in the context of systemic inflammation, using sepsis and COVID-19 as prototypical diseases." (PMID 38598083, 2024). "The dysregulated immune response characteristic of severe COVID-19 involves a cytokine storm, marked by an excessive release of proinflammatory cytokines (e.g. IL-6,TNF-alpha)." (PMID 39359765, 2024). "Tocilizumab, an interleukin-6 inhibiting monoclonal antibody, is suggested for use in the treatment of COVID-19, particularly in patients with macrophage activation syndrome." (PMID 38433274, 2024). "The main cytokines involved in the COVID-19-driven inflammatory response have been identified as interleukin 6 and interleukin 1b (IL-1b)." (PMID 39967901, 2024). "ORF3a-mediated signaling pathways involve key cellular regulators such as NLRP3, NF-κB, and related cytokines (TNFα and IL-6), all well-known druggable cellular targets relevant to COVID-19." (PMID 38251382, 2024). "Our study aimed to measure NEAT-1, miR-374b-5p, and IL6 in the serum of COVID-19 patients, demonstrating the correlation between target genes to explore the possible relationship between them." (PMID 39729489, 2024). "We recommend paying special attention for the occurrence of secondary IFI in COVID-19 patients with low BMI (BMI < 28 kg/m2), elevated log IL-6 levels and fever." (PMID 39040601, 2024). "Notable among the metabolites interacting with IL6 is taurine, an amino sulfonic acid involved in the regulation of oxidative stress, which is known to play an important role in COVID-19." (PMID 39040605, 2024). "A meta-analysis reviewed multiple studies and found that CRP, IL-6, NLR, and LDH levels consistently indicate severe COVID-19, supporting their use in clinical risk assessment models." (PMID 39594223, 2024). "The ability of predictors to discriminate ACS in COVID-19 patients was determined using a receiver-operating characteristic (ROC) curve based on logistic regression models for IL-6 alone and in combination with other predictors." (PMID 39395941, 2024). "In this study, we analyzed serum levels of IL-6, sIL-6R and sgp130 in the serum of COVID-19 convalescent individuals with a history of mild COVID-19 disease and in acute severely ill COVID-19 patients compared to uninfected control subjects." (PMID 39835136, 2024).
COVID-19 (continued). "As a result, tocilizumab blocks both pathways, thereby reducing IL-6-driven hyperinflammation, which is crucial in managing severe COVID-19 complicated by ARDS." (PMID 39767830, 2024). "Analysis of the GEO database revealed elevated expression levels of pro-inflammatory cytokine genes, including interleukin-1α (IL-1A), IL-1β, and IL-6, in individuals with severe COVID-19 compared to healthy controls." (PMID 39519351, 2024). "The crucial role of NF-κB inhibition in reducing highly pro-inflammatory cytokine such as IL-6 has been recently highlighted for treatment of critical stage COVID-19 patients." (PMID 38164360, 2024). "Immunosuppressants are predisposing factors in this context, and these were recommended as adjunctive therapies in severe COVID-19 patients as early as 2020 (dexamethasone) and 2021 (anti-IL-6)." (PMID 39335010, 2024). "Cytokine IL-6 plays a vital role in hypercoagulability by magnifying fibrinogen and platelet production and is positively correlated with COVID-19 severity." (PMID 38255892, 2024). "IL-6 also confirmed a significant prognostic value, showing a significant decrease in COVID-19 patients at later time points." (PMID 39582872, 2024). "While previous studies have identified cytokines like IL-6, IL-10, and TNF-α as early severity predictors or associated with mortality in severe COVID-19, this study emphasizes the unique contribution of sTNFRI and sTNFRII levels." (PMID 39335653, 2024). "A meta-analysis showed that increased IL-6 correlates with long COVID-19, suggesting IL-6 as a basic determinant predicting long COVID-19." (PMID 39199353, 2024). "Emerging clinical cut-off values for IL-6 are being proposed to guide therapeutic interventions in COVID-19 patients." (PMID 39458339, 2024). "A study on 89 COVID-19 patients with lung damage of varying degrees revealed that the levels of IL-6 signaling components (IL-6, sIL-6R, and sgp130) correlated with lung damage." (PMID 39518964, 2024). "Mean [± SEM] IL-6 concentrations in the pooled sepsis subgroup were higher than in the COVID-19 subgroup (2859 [± 1275] vs. 636 [± 476] ng/ml)." (PMID 38598083, 2024). "The biomarker with the best discrimination capacity for severe COVID-19 was IL6, with an AUROC of 0.79 (95%CI: 0.66 to 0.93), closely followed by IP10 and CRP (AUROCs of 0.78, 95% CI 0.68 to 0.89; and 0.78, 95% CI 0.67 to 0.89)." (PMID 39664394, 2024). "For example, elevated levels of inflammatory markers, such as CRP and interleukin-6 (IL-6), have been observed in cancer patients with COVID-19, indicating a heightened inflammatory response." (PMID 39655133, 2024). "In vitro pharmacological IL-6 blockade protected against eGC damage induced by sera from bacterial sepsis and COVID-19 patients." (PMID 38598083, 2024). "In critically ill COVID-19 patients, naringenin also showed excellent IL-6 inhibition compared to synthetic monoclonal antibodies." (PMID 38399736, 2024). "Here we identify S protein as a direct stimulator of monocyte activation by triggering the NF-κB pathway and releasing cytokines such as IL-6, which is elevated in the circulation of COVID-19 patients where it correlates with T cell depletion." (PMID 38225643, 2024). "The progression of COVID-19 is often accompanied by an upsurge in proinflammatory endogenous cytokines, including interleukin-1 (IL-1), interleukin-6 (IL-6), and tumor necrosis factor-alpha (TNF-alpha)." (PMID 38511750, 2024). "Overactivation of IL-6 is a pivotal mediator in the development of COVID-19 into respiratory failure, shock, and multiple organ dysfunction." (PMID 39040601, 2024). "By ingesting 10 g of glutamine three times daily, COVID-19 patients presenting pulmonary infections can reduce their concentrations of IL-6, TNF-a, and hs-CRP and increase their appetite." (PMID 38390861, 2024). "Our study showed an association between high levels of both IL-6 and PCT and a severe course or even death in COVID-19 patients at the time of hospital admission." (PMID 38433829, 2024).
COVID-19 (continued). "We monitored and detected the expression levels of IP-10, MCP-1, MIG, sCD25, sTREM-1, and IL-6 in the serum of 9 COVID-19 patients upon admission and before discharge." (PMID 39654886, 2024). "Our results clearly showed that a lower EPA/AA ratio, mainly observed in Groups 4–5, was associated with a higher concentration of IL-6 and CRP, typically elevated in critically ill COVID-19 patients, bringing a worse prognostic to these patients." (PMID 38702342, 2024). "IL-6 is increased in patients with liver cirrhosis and IL-6 was almost 2-fold higher in severe COVID-19 cases compared to moderate cases after excluding patients with liver cirrhosis." (PMID 38791005, 2024). "A different study showed increased levels of inflammatory markers such as C-reactive protein, D-dimer, ferritin, IL-6 and lactate dehydrogenase (LDH) associated with higher mortality in COVID-19 patients." (PMID 37938797, 2024). "Co-administration of an IL-6 inhibitor (siltuximab) and an IL-6 receptor inhibitor is potent enough to treat COVID-19 patients with acute respiratory distress syndrome." (PMID 38392902, 2024). "Among these cytokines, IL-6 has emerged as a key mediator of the cytokine storm in COVID-19, and its levels have been shown to correlate with disease severity and mortality." (PMID 39130641, 2024). "The GSH precursor N-acetylcysteine (NAC) has anti-ferroptotic effects via the direct reinforcement of the cystine–GSH–GPX4 axis and the reduction of IL-6-induced ROS production, which is related to its efficiency in treating COVID-19." (PMID 39516736, 2024). "Due to the abundant expression of ACE2, COVID-19 can induce tissue injury and immune dysregulation, resulting in highly elevated levels of inflammatory cytokines, such as IL-6 and CRP, as well as increased NLR." (PMID 37702601, 2024). "In the context of COVID-19 hyperinflammation, several agents, including the anti-IL-6 monoclonal antibodies tocilizumab and dexamethasone, have demonstrated efficacy and are being utilised in clinical practice." (PMID 39000566, 2024). "They note that severe COVID-19 patients exhibit extremely high levels of proinflammatory cytokines like IL-6 and TNF-α." (PMID 39350850, 2024). "COVID-19 induces uncontrolled inflammation, a so-called cytokine storm, including IL-6, IL-1b, IL-2, IL-10, TNF-α and monocyte chemoattractant protein (MCP-1)." (PMID 38732160, 2024). "This is consistent with other studies that have identified IL-6 as a central mediator of the cytokine storm, often observed in severe cases of COVID-19, which leads to acute respiratory distress syndrome (ARDS) and other critical complications." (PMID 39062105, 2024). "We observed reduced serum iron, TSAT and hemoglobin concentrations as well as raised ferritin, hepcidin and IL-6 in COVID-19 severity groups C–E from day 0–14 post symptom onset, indicating inflammatory anemia in moderate–severe disease." (PMID 38429458, 2024). "In the present study, we analyzed IL-6, IL-11, sIL-6R, sgp130 and sCD25 in the serum of healthy, uninfected subjects, in COVID-19 convalescent individuals with a history of mild COVID-19 disease and in acute severely ill COVID-19 patients." (PMID 39835136, 2024). "Further, bio-ADM and IL-6 each were significantly elevated in patients with COVID-19, who reached either of the individual endpoints admission to the ICU or in-hospital death." (PMID 38336628, 2024). "Our study aimed to investigate the variability in serum levels of IL-6 and its soluble receptor complex among COVID-19 patients across different waves of the pandemic." (PMID 39063569, 2024). "Hypoalbuminemia has previously been reported as a predictive marker of COVID-19 mortality, and COVID-19 patients who received albumin infusions have been shown to have reduced IL-6 and IL-2R concentrations." (PMID 39345212, 2024).